LEP (leptin)
Diseases named in the same sentence as LEP in open-access papers (continued):
Sharing a sentence is not in itself a finding about the gene and the disease.
Obesity (continued). "Women with obesity tend to have elevated leptin levels and may exhibit leptin resistance." (PMID 40868103, 2025). "However, in cases of obesity, the development of leptin resistance occurs: this is thought to be due to impaired intracellular signal transduction and reduced leptin transportation to the brain via the blood-brain barrier, rendering the body less responsive to its signals." (PMID 40969606, 2025). "Considering the effects of leptin and IGF-1 on fetal insulin resistance and lipid metabolism, increased levels of leptin and IGF-1 are potential plasma biomarkers of increased fetal adiposity, which may predispose to infant obesity and metabolic dysfunction in later life." (PMID 40725173, 2025). "Finally, obesity alters the secretion of adipokines such as adiponectin and leptin." (PMID 39857741, 2025). "Among determinants of excessive placental weight, higher amounts of nutrients and high concentrations of leptin produced by adipose tissue in mothers affected by obesity could promote proliferation of trophoblasts, which contribute to the increased placental weight." (PMID 40078195, 2025). "In general, obesity is associated with dysfunction of the hypothalamic–pituitary–adrenal (HPA) axis with a reduced response to cortisol feedback with the immune system (chronic low-grade inflammation) and dysregulation of metabolic pathways (leptin, insulin, NPY, and ghrelin, among others)." (PMID 41373743, 2025). "The differences in the effects between diet-induced and genetic obesity on ovarian reserve may be influenced by leptin, as diet-induced obesity is often accompanied by elevated circulating leptin levels, which may accelerate follicular overactivation through stimulation of the HPO axis." (PMID 41321496, 2025). "Changes in concentrations of adipokines such as leptin which may be a link between obesity and other metabolic disturbances, e.g. via the proinflammatory properties of leptin it may be involved in development of dyslipidemia, insulin resistance and cardiovascular complications." (PMID 39899498, 2025). "Leptin and its receptor are key components in regulating energy homeostasis, and any disruption in their signaling pathway can lead to the development or exacerbation of the metabolic diseases such as obesity, T2DM, metabolic syndrome, non-alcoholic fatty liver disease, and CVD." (PMID 41158627, 2025). "Of note, previous studies have suggested the existence of non-homeostatic reward-related hyperphagia and associated obesity development, which may also serve as an additional neural basis of leptin-insensitive leptin resistance." (PMID 40540394, 2025). "However, excessive LEP levels, such as those observed in obesity, can lead to LEP resistance, which may impair reproductive function." (PMID 40689179, 2025). "This supports the hypothesis that ciliopathies, such as BBS, involve intrinsic defects in leptin and insulin pathways that are exacerbated, rather than solely caused, by obesity." (PMID 40233116, 2025). "Additionally, the inflammatory markers (TNF-α and leptin) were elevated in cases with obesity." (PMID 41334630, 2025). "It is conceivable that the M4-KO mice may develop leptin resistance before the onset of obesity." (PMID 40179260, 2025). "In a recent study of Norwegian children and adolescents, blood concentrations of leptin, IGF-1 and triglycerides were also positively associated with each-other and negatively associated with HDL-cholesterol concentrations, and were particularly elevated in children with overweight/obesity." (PMID 39899498, 2025). "Additionally, leptin has pro-inflammatory properties and is directly involved in the development of both hypertensive retinopathy and diabetic retinopathy in individuals with obesity." (PMID 40724604, 2025).
Obesity (continued). "By contrast, other studies have shown that global GIPR-KO mice are protected from both obesity and insulin resistance when fed a high-fat diet, and GIPR antagonism coupled with GLP-1R agonism leads to weight loss in early clinical trials and mouse models, possibly by preventing leptin resistance." (PMID 40857106, 2025). "However, in pathological conditions—such as obesity or metabolic syndrome—elevated leptin levels become pro-inflammatory, increasing the production of pro-inflammatory cytokines, such as TNF-α and IL-6, exacerbating vascular inflammation and contributing to the development of atherosclerosis." (PMID 40943241, 2025). "Notably, obesity-related metabolic abnormalities (e.g., lipid deposition and leptin resistance) may further exacerbate white matter injury." (PMID 40734944, 2025). "Therefore, we measured blood glucose and leptin levels to examine the effect of MCFAs on obesity." (PMID 40427263, 2025). "Moreover, an MC4R agonist, setmelanotide (Set), which has a 20-fold MC4R selectivity compared with α-MSH, has been effective for weight loss in patients with the MC4R/POMC/leptin pathway polymorphism and has been approved by the FDA for treatment of obesity in these patients." (PMID 40232848, 2025). "Additionally, obesity and insulin resistance compound acne-related inflammation through the secretion of pro-inflammatory adipokines like leptin, which promotes Th1 and Th17 polarization and increases cytokines such as interferon-gamma (IFN-γ), IL-17, and IL-22." (PMID 39858932, 2025). "Thus, hyperinsulinemia and hyperleptinemia in the milk of obese mothers, which reflects their insulin and leptin resistance, may possibly expose their infants to developmental programming of obesity in later life." (PMID 40077697, 2025). "Moreover, within the context of obesity, heightened leptin secretion and/or diminished lipocalin synthesis by adipocytes may directly or indirectly impinge upon bone formation via the upregulation of proinflammatory cytokine generation." (PMID 40040838, 2025). "Pro-inflammatory factors and leptin might play roles between obesity and RCC." (PMID 40933888, 2025). "However, the leptin-deficient model does not accurately replicate the complexities of obesity in humans." (PMID 41155630, 2025). "Interestingly, leptin-deficient animals and humans have lower blood pressure despite severe obesity, though the link between chronic high leptin levels, leptin resistance, and hypertension remains unclear." (PMID 41155389, 2025). "Additionally, its protective or detrimental effects likely depend on whether it acts under physiological conditions or in the context of obesity-induced leptin resistance." (PMID 41516046, 2025). "In mothers with obesity, prolonged inflammation within the mammary gland, a blunted hormonal response (notably of prolactin), altered progesterone and estrogen dynamics, high leptin levels, and misaligned circadian rhythms contribute significantly to delayed lactogenesis." (PMID 40868103, 2025). "However, only IL-6, leptin, adiponectin, and resistin serum levels were found to be significantly associated with diabetes without obesity, after adjusting for age." (PMID 40095937, 2025). "Furthermore, the frequent and excessive overconsumption of unhealthy foods leads to metabolic diseases, obesity, hypercholesterolemia, type 2 diabetes, hyperuricemia, hormonal disorders such as insulin resistance, leptin and ghrelin imbalances, and cardiovascular diseases, among others." (PMID 39856976, 2025). "Specifically, homozygous loss-of-function (LoF) mutations in genes such as LEP, LEPR, and homozygous and heterozygous in MC4R result in uncontrollable hyperphagia, an eating disorder characterized by excessive hunger and food intake, leading to extreme early-onset obesity." (PMID 39237720, 2025).
Obesity (continued). "Relative to those in the normal control group, the rats in the model group showed decreases in CCK and GLP-1 levels, and increases in leptin, ghrelin and orexin A levels, indicating that obesity could result in the imbalance in appetite-related gastrointestinal hormones." (PMID 40176906, 2025). "This review examines how yoga might affect leptin and adiponectin levels in people with obesity." (PMID 39897330, 2025). "Additionally, in obese patients, leptin may contribute to obesity-related glomerulopathy, potentially stimulating the renin–angiotensin–aldosterone system and exacerbating proteinuria and CKD." (PMID 40867871, 2025). "However, only IL-6, leptin, adiponectin, and resistin serum levels were found to be significantly associated with diabetes without obesity, even after adjusting for sex (Model 2) or age (Model 3)." (PMID 40095937, 2025). "Second, obesity-induced leptin resistance may have contributed to decreased impulsivity." (PMID 39780112, 2025). "The present project hypothesizes that the combination of ST and CT with Intensive Health Behavior Treatment (IHBT; 26), which includes PA and dietary interventions, will lead to an improvement in leptin sensitivity in children following treatment for overweight and obesity." (PMID 40607230, 2025). "Furthermore, sleep insufficiency may also affect adipokine levels, such as increased leptin and decreased adiponectin, contributing to obesity and insulin resistance." (PMID 41209443, 2025). "However, given leptin’s established role in metabolic reprogramming of lymphocytes, leptin resistance in obesity may impair ML NK cell development, thereby suppressing their antiviral and antitumor immunity." (PMID 41516046, 2025). "In addition to mechanical effects, obesity might activate bone formation via endocrine mechanisms mediated by insulin, leptin, and estrogen." (PMID 41441007, 2025). "This study aimed to measure and compare circulating leptin levels between Bangladeshi young individuals with a clinical diagnosis of new-onset T2DM and normal glucose tolerance (NGT), and to investigate the associations of leptin with obesity markers, glycemic parameters, and insulin resistance." (PMID 40630340, 2025). "In humans, a single-nucleotide polymorphism (rs10487505) in the corresponding region is associated with circulating leptin levels and obesity in a sex-specific manner but not with leptin gene expression, suggesting post-transcriptional mechanisms, e.g. the regulation of long non-coding RNAs." (PMID 39934931, 2025). "We hypothesize that serum leptin levels are associated with impaired lipid metabolism and renal function in individuals with T2DM and that this association may be influenced by the presence of obesity." (PMID 41239622, 2025). "Likewise, leptin-based therapies may be beneficial in people with severe obesity and leptin resistance." (PMID 40013194, 2025). "Finally, another mechanism that may explain this relationship is the elevated leptin concentrations found in individuals with obesity." (PMID 41227253, 2025). "The role of adipose-derived leptin, which is elevated in obesity, may impact the onset of puberty." (PMID 41573206, 2025). "Thus, SOCS3 may contribute to the development of diet-induced obesity and hypothalamic leptin resistance." (PMID 40690443, 2025). "ER stress in the hypothalamus may be a key mechanism contributing to leptin resistance and obesity." (PMID 41018420, 2025). "Interestingly, hyperleptinemia was observed also in individuals with obesity, thus hypothesizing a condition of “leptin resistance”, meaning an abnormal increase in leptin levels without a decrease in appetite or an increase in energy expenditure." (PMID 39941454, 2025). "Notably, EE has been shown to programme hypothalamic leptin sensitivity most effectively when performed within a critical juvenile period, suggesting that a similar approach should be adopted in humans with obesity or overweight." (PMID 40607230, 2025).
Obesity (continued). "However, leptin and insulin resistance are common in obesity, where the effects of leptin and insulin within the AC, and especially in the POMC/CART neurons, become less pronounced and sometimes these effects may even be absent." (PMID 40136445, 2025). "Our results propose a mechanism for leptin delivery via EVs, offering a significant advancement in understanding how EVs released by obese AT act in promoting breast cancer malignancy and providing new insights into the interplay between obesity, leptin signaling, and tumor progression." (PMID 40485730, 2025). "Herbal compounds like celastrol, extracted from Tripterygium wilfordi, have been identified for their potential in obesity treatment by enhancing leptin sensitivity and inhibiting new blood vessel growth, which may contribute to their effectiveness in reducing fat mass." (PMID 40016558, 2025). "Spectral analysis revealed 2 components (periodicities: 24 and 12 hours) with higher relative amplitudes in lean than in subjects with obesity suggesting that attenuated or altered circadian rhythmicity might play a role in the development of leptin resistance and obesity." (PMID 40251987, 2025). "However, as leptin’s role alone and in its relationship with obesity in cancer development and therapy remains unclear, more research is needed." (PMID 40783771, 2025). "Notably, leptin-treated NachBac mice showed a p-STAT3 expression level comparable to that of leptin-treated ob/ob mice, demonstrating that, despite severe obesity development and phenotypic leptin resistance, leptin-induced p-STAT3 signaling remains intact in Arc LepR neurons." (PMID 40540394, 2025). "It was ascertained that in vivo PTP1B deficiency or silencing can result in enhanced signal transduction of both leptin and insulin, thus improving glucose homeostasis and providing resistance to diet-induced obesity, without causing abnormalities in growth or other vital functions." (PMID 41302504, 2025). "This might be due to patients with common obesity not being leptin deficient, but on the contrary having high leptin levels and being leptin resistant." (PMID 39929239, 2025). "Additionally, elevated leptin concentrations in obesity may induce leptin resistance in the hypothalamus, further impairing GnRH and subsequent LH secretion." (PMID 40723795, 2025). "Furthermore, obesity reduces serum adiponectin and increases serum leptin." (PMID 40002337, 2025). "Thus, PTPRJ induction is implicated in the development of leptin resistance, and PTPRJ inhibition may be a potential strategy for improving obesity." (PMID 39897330, 2025). "Clearly therefore, much needs to be understood regarding the roles of obesity and leptin signaling in the lungs, especially whether the obesity paradox results from a direct deleterious effect of increased levels of leptin or from leptin resistance." (PMID 40635334, 2025). "Furthermore, sleep deprivation or chronodisruption may dysregulate ghrelin-leptin signaling, exacerbating lipid metabolism disturbances and elevating risks of dyslipidemia, obesity, and related cardiovascular sequelae." (PMID 40496559, 2025). "Moreover, leptin can regulate lipid metabolism, our model does not allow us to specifically define what aspects of tubular lipidome changes are related to obesity and leptin deficiency." (PMID 41213922, 2025). "Obesity may impede an individual’s capacity to generate an effective immune response to vaccination or infection, a phenomenon attributable to increased body fat and elevated leptin levels." (PMID 39859575, 2025). "Reducing leptin resistance is crucial for treating obesity; thus, the significant decrease in leptin levels under olivetol administration, along with the body weight loss observed in the HFD-fed group of mice, may indicate an improvement in leptin resistance." (PMID 39857767, 2025).
Obesity (continued). "We then hypothesized that leptin, highly elevated in patients with obesity and, in our studies, markedly correlated with higher CCL2/MCP‐1 expression in both plasma and vWAT, as well as in ASCs, increases the expression of this chemokine in ASCs by regulating H3K27 acetylation." (PMID 40518865, 2025). "The mechanisms underpinning this protective effect are poorly understood, but postulated reasons include higher leptin levels in obesity affecting host immunity and adipose tissue acting as a reservoir in which Mycobacterium tuberculosis may persist without causing disease." (PMID 40922029, 2025). "High levels of leptin in the obesity microenvironment increase the expression of PD1 receptors and the depletion of T cells, which may be harmful to the immunotherapy based on Chimeric Antigen Receptor T-cells (Car-T cells) and bispecific T-cell engagers (BiTE)." (PMID 41200178, 2025). "However, obesity impaired the effect of excess leptin in the neuron." (PMID 40811476, 2025). "Obesity increases arterial stiffness due to endothelial dysfunction, impaired vascular smooth muscle cell function, IR, elevated cholesterol, C-peptide levels, fat distribution, adipose tissue-related renin-aldosterone-angiotensin system, and increased leptin levels." (PMID 39335575, 2024). "Notably, improvements induced by HB in insulin sensitivity, fasting blood glucose levels, leptin, and adiponectin effectively prevented insulin resistance, reduced weight gain, and improved glycolipid metabolism and antioxidant capacity in rats with obesity." (PMID 39458511, 2024). "Additionally, we explored whether these effects are modulated by H3K27 modifications and the impact of leptin (whose secretion is high in the WAT of obesity individuals) on ASCs." (PMID 39065712, 2024). "Therefore, we propose inclusion of leptin responsiveness assessments in clinical trials for anti-obesity medications by measuring SLR as it could serve as a biomarker of leptin responsiveness." (PMID 39183855, 2024). "Gene editing or specific inhibitors could be applied to our system to define the effects of adipokines such as adiponectin, leptin, resistin and omentin or metabolic and inflammatory pathways that impact hepatic insulin response in the setting of obesity and WAT inflammation." (PMID 39266553, 2024). "This may contribute to a better characterization of the influence of obesity on leptin secretion." (PMID 39281006, 2024). "Thus, obesity and pregnancy contribute to increased leptin plasma levels." (PMID 39083072, 2024). "Similarly, rare mutations causing congenital leptin deficiency or leptin resistance in humans are associated with rapid weight gain, severe obesity, low gonadotropin levels, and delayed or absent puberty." (PMID 38131197, 2024). "In addition, in obesity, pro-inflammatory mediators (leptin, resistin, IL-6, and TNF-α) may promote adipose tissue dysregulation and systemic insulin resistance." (PMID 39065815, 2024). "In addition, obesity and pathologic fat accumulation lead to decreased function of astrocyte-neuron crosstalk, in which high serum levels of leptin inhibit astrocyte excitatory amino acid transporter protein (EAAT) expression and promote sympathetic overactivation." (PMID 38800473, 2024). "In our study, obesity history in the family did not affect LEP gene methylation or polymorphisms." (PMID 39594868, 2024). "However, leptin resistance is also reported to contribute to hypertension in Bardet-Biedl syndrome mouse models, suggesting that obesity paradox may be at play, or leptin's effects can vary depending on different physiological backgrounds." (PMID 39655343, 2024). "It is established that obesity is associated with a state of chronic inflammation in the patient, characterized by the accumulation of M1-polarized macrophages, Tregs, and the secretion of proinflammatory factors, including TNF-α, IL-6, IL-1β, and leptin, which have all been linked to CRC." (PMID 39201522, 2024).